RNU7-126P (RNA, U7 small nuclear 126 pseudogene)
Gene: Small nuclear RNA gene on chromosome 4 (25,598,564 to 25,598,625, reverse strand). Ensembl gene ENSG00000238632.
Homologues: Orthologues: chimpanzee U7 (89% identical). Paralogues in human: RNU7-14P (77% identical), RNU7-23P (77% identical), RNU7-49P (77% identical), RNU7-7P (77% identical), RNU7-8P (77% identical), RNU7-1 (76% identical), RNU7-10P (76% identical), RNU7-128P (76% identical), RNU7-18P (76% identical), RNU7-20P (76% identical), RNU7-28P (76% identical), RNU7-143P (74% identical), and 142 more.